TCF4 (transcription factor 4)
Diseases named in the same sentence as TCF4 in open-access papers (continued):
Sharing a sentence is not in itself a finding about the gene and the disease.
schizophrenia (continued). "Finally, the miR-137 validated target PKA signaling gene set (MAPK1, MAPK3, TCF4, and PTGS2) is of particular interest given that enrichment of schizophrenia-risk associated variants within these targets was replicated in an independent cohort." (PMID 25941532, 2015). "In fact, TCF4, one of only three genes correlated with schizophrenia at the whole genome level, had a large expression effect (r = −0.43; data not shown) for negative symptoms suggesting that a significant correlation may have been observed in a larger sample." (PMID 24236287, 2013). "Furthermore, adult mice moderately over-expressing TCF4 in the brain have behavioural abnormalities including deficits in sensory-motor gating and cognitive performance, reminiscent of certain schizophrenia endophenotypes." (PMID 24058414, 2013). "Several molecular pathways have been implicated in abnormal synaptic pruning in schizophrenia, including complement C4A overexpression, kynurenine pathway imbalance (KYNA/QUIN), and dysregulation of microglial and transcriptional modulators such as MEF2C and TCF4." (PMID 41169352, 2025). "Thus, the aim of our pilot study was to analyze the possible associations between positive and negative schizophrenia symptoms and polymorphic variants of the TCF4 gene." (PMID 41226544, 2025). "For example, TCF4 haploinsufficiency results in Pitt-Hopkins syndrome (MIM #610954), a severe neurodevelopmental disorder, whereas somatic TCF4 mutations are commonly identified in Sonic hedgehog medulloblastoma and common germline variants have been associated with Schizophrenia risk." (PMID 38713708, 2024). "Additionally, it has been noted that TCF4 overexpression in the brain results in memory problems and, more significantly, prepulse inhibition problems, which are neurophysiological correlates of schizophrenia and other psychiatric illnesses." (PMID 37780577, 2023). "Genetic mutations in TCF4 have been reported in neurological disorders, including Fuchs’s corneal dystrophy, Pitt–Hopkins syndrome, and schizophrenia, as well as non-neurological diseases, including primary sclerosing cholangitis and sporadic Sonic Hedgehog-associated medulloblastoma (SHH MB)." (PMID 36084949, 2022). "Transcription factor 4 (TCF4) is vital for normal development of the central nervous system, and the mutations within the TCF4 gene have been linked to several neurodevelopmental diseases such as Pitt-Hopkins syndrome (PTHS), mild-to-moderate intellectual disability (MMID), and schizophrenia (SCZ)." (PMID 34748727, 2021). "Here, we provide scRNA-Seq and biochemical evidence that the transcription factor TCF4, which has been linked with schizophrenia, autism and intellectual disability, engages in non-canonical interactions with non-bHLH TFs to regulate the development of interhemispheric connectivity." (PMID 34184026, 2021). "The role of TCF4 in neural development is not currently well understood, although loss-of-function mutations of this gene have been shown to be responsible for severe neurodevelopmental disorders, as well as conferring risk of schizophrenia." (PMID 34088262, 2021). "Therefore, in the present study, TCF4 and NRXN1 genes were selected and a correlation study of rs13381800 in the promoter region of TCF4 gene with rs17039988 in the promoter region of NRXN1 gene was performed in samples collected from individuals with schizophrenia and healthy controls." (PMID 32071599, 2019). "TCF4 haploinsufficiency causes PTHS, while SNPs in regulatory regions, which may cause increased TCF4 expression, are associated with an elevated risk for schizophrenia." (PMID 29588831, 2018). "Therefore, to gain a functional insight into the role of TCF4 in schizophrenia other neurodevelopmental disorders, we used a bespoke TCF4 antibody for chromatin immunoprecipitation and next generation sequencing (ChIP-seq) to define the genomic targets of TCF4." (PMID 29228394, 2018).
schizophrenia (continued). "For example, TFs SMARCA1, TCF4, and TRPS1 have been confirmed to play crucial roles in schizophrenia, and they have been confirmed to target CRABP1." (PMID 39905509, 2025). "A meta-analysis of 18 GWASs for schizophrenia supported involvement of the MHC region, TCF4, POM121L2, NOTCH4, AS3MT, CNNM2, and NT5C2." (PMID 27064909, 2016). "However, the elevated risk for schizophrenia was not conferred by TCF4-mediated VDM impairment." (PMID 24403877, 2013). "Thus, alterations in the activity or levels of TCF4 as seen in PTHS, autism and possibly schizophrenia, may be associated with dysregulation of several transcription factors that control neurodevelopmental gene expression programs at E-box containing promoters." (PMID 24058414, 2013). "In conclusion, depending on the collected data, it was revealed that rs13381800 SNP in TCF4 gene and rs17039988 SNP in NRXN1 gene were not risk factors for schizophrenia in this sample of Iranian patients with schizophrenia." (PMID 32071599, 2019). "Corresponding results in clinical studies suggested a critical effect of TCF4 in several phenotypes of schizophrenia, including age at onset, sensorimotor gating, negative symptoms, cognitive function and MRI-measured brain structure." (PMID 31191620, 2019). "In the present study, it was hypothesized that there is a correlation between rs13381800 in the promoter region of the TCF4 gene and rs17039988 in the promoter region of the NRXN1 gene and schizophrenia." (PMID 32071599, 2019). "The data for inherent, absolute “baselines” of expression between medial and lateral rectus muscles revealed two genes with similar directionalities between EOMs and schizophrenia (NPYR1, NTRK2), while two others (TCF4, TIMP2) went in the opposite direction (slight increase in blood)." (PMID 29302405, 2017). "According to a study of convergent functional genomics, among the most promising candidate genes known to play a role in the disorder are disrupted-in schizophrenia (DISC1), transcription factor 4 (TCF4), myelin basic protein (MBP) and heat-shock 70-kDa protein 1B (HSPA1B)." (PMID 25658856, 2015). "Moreover, four other schizophrenia associated genes (TCF4, CACNA1C, CSMD1, and C10orf26) identified in that study contain predicted miR-137 binding sites, suggesting that the interplay between miR-137 and its target genes could be involved in the etiology of schizophrenia." (PMID 25250332, 2014). "In this study, we have shown that genetic variation in schizophrenia risk genes MIR137, TCF4, and ZNF804A does not lead to alterations in TBV, GM, WM, or hippocampal brain volumes as measured with structural MRI in healthy young adults." (PMID 25217366, 2014). "There was significant heterogeneity among the gene sets, with the TCF4 gene set, the FMRP gene set, the gene set upregulated in the presence of excess MIR137 and the gene set downregulated in the absence of CHD8 shown to be associated with schizophrenia." (PMID 31078131, 2019).
colorectal cancer (120 papers, 2005 to 2026). A primary or metastatic malignant neoplasm that affects the colon or rectum. "Studies have shown that fusion of the VTI1A and TCF7L2 genes, encoding a VTI1A-TCF4 fusion protein containing truncated TCF4, regulates the Wnt signaling pathway and participates in colorectal cancer development." (PMID 35711736, 2022). "Previous studies reported high frequency of mutations (10%) in exon 1 of the TCF-4 gene in colorectal cancer compared to other exons (2–3%)." (PMID 32265994, 2020). "Aberrant activation of β-catenin/Tcf-4 signaling has been implicated in human carcinogenesis, including colorectal cancer." (PMID 23029137, 2012). "In colorectal cancer, activating mutations in Wnt pathway components cause inappropriate activation of TCF4/β-catenin-driven transcription." (PMID 21103407, 2010). "The strong correlation between PKCδ and TCF4 implies that PKCδ may be associated with Wnt/β‐catenin signaling in colorectal cancer cells." (PMID 38425293, 2024). "The strong correlation between TCF4 and PKCδ suggests that PKCδ may be associated with Wnt/β‐catenin signaling in colorectal cancer cells." (PMID 38425293, 2024). "GEO survival analysis was conducted to screen TCF4 target genes associated with the survival of colorectal cancer patients, among which Cystic fibrosis transmembrane conductance regulator (CFTR), Tyrosine-protein kinase Fyn (FYN), and YOD1 deubiquitinase (YOD1) were considered to be eligible." (PMID 37337284, 2023). "TCF-4, a tumor suppressor and a DNA binding factor, which is a cell-specific key downstream effector of the Wnt/β-catenin pathway, upon modulation causes a critical event in colorectal cancer (CRC) development in humans." (PMID 32265994, 2020). "An association of two non-coding SNPs in the TCF-4 gene has been observed with diabetes mellitus and, in another study, an association with deletions and insertions of adenines in the coding region was reported in patients with colorectal cancer." (PMID 19221600, 2009). "As a very important signaling pathway, Wnt/β-catenin/TCF4 plays a pivotal role in kinds of human malignancies such as breat cancer, hepatocarcinoma, endometrial carcinoma, colorectal cancer as well as MM." (PMID 41535418, 2026). "Expression of CD44v isoforms is reported to be regulated by the Wnt-β-catenin/TCF4 signaling pathway in colorectal cancer." (PMID 41369362, 2025). "SHMT2 can participate in the interaction between transcription factor TCF4 and β-catenin, enhancing its own expression and promoting the growth and metastasis of colorectal cancer cells." (PMID 38594513, 2024). "Specifically, β‐catenin/TCF4 triggers the transcription of PKM2 to enhance the Warburg effect in colorectal cancer." (PMID 38733179, 2024). "Survivin is one of the target genes of the TCF4/β‐catenin complex and is upregulated in colorectal cancer SW480 and HCT‐116 cells compared with normal CCD841 cells." (PMID 38425293, 2024). "lncRNA CRNDE, a molecular sponge of miR-181a-5p, is involved in regulating the expression of T cell factor 4 (TCF4)and β-catenin and regulates the proliferation and chemo-resistance in colorectal cancer by affecting the WNT/β-catenin signaling pathway." (PMID 37914721, 2023). "As determined by the results of in vitro and in vivo studies, TCF4 is important for the development of colorectal cancer." (PMID 37337284, 2023). "Tribbles pseudo-kinase 3 (TRIB3) can then interact with β-catenin/TCF4 to increase stem cell features of colorectal cancer stem cells and tumorigenesis." (PMID 37337284, 2023).
colorectal cancer (continued). "In colorectal cancer, TCF4 promotes liver metastasis by recruiting TAMs and polarization of M2 macrophages via the CCL2-CCR2 axis." (PMID 37415241, 2023). "Taken together, these results suggested that oridonin decreases the tumorigenesis and aggressiveness of colorectal cancer cells by declining the inhibition of TCF4 on ER stress." (PMID 37337284, 2023). "During glutaminolysis inhibition in colorectal cancer, activating transcription factor 4 (ATF4) is increased to reduce mTOR signaling by transcriptionally activating the mTOR suppressor DNA damage-inducible transcript 4 (DDIT4)." (PMID 36900220, 2023). "rhREG4 treatment promoted G2 progression for the mitogenesis of colorectal cancer cells by Akt/glycogen synthase kinase three β (GSK3β)/β-catenin/transcription factor 4 (TCF-4) signaling." (PMID 36172286, 2022). "Several recent studies have reported the anti-tumorigenesis role of TCF4 in colorectal carcinoma and SHH MB." (PMID 36084949, 2022). "In contrast, the oncogenic role of TCF4 has been shown by inducing cell proliferation in colorectal cancer, EMT in MDCK normal kidney cells, and distant metastasis in malignant melanoma." (PMID 33917757, 2021). "β-catenin is the molecular hub of the Wnt signaling pathway, and TCF4 is a transcription factor of the Wnt pathway, which is highly expressed in colorectal cancer." (PMID 34686186, 2021). "To investigate the role of TCF4 in colorectal cancer liver metastasis, we compared TCF4 expression in human primary colorectal cancer and hepatic metastasis samples." (PMID 34580284, 2021). "In colorectal cancer, the β-catenin/TCF4 complex regulates the expression of EphB/EphrinB, which is upregulated in early adenomas and plays an important role in colorectal cancer progression." (PMID 34149921, 2021). "It’s worth to investigate the targets of ZEB1 regulating by cooperation of METTL14, YHTDF2, ARRDC4, TCF4 and HuR leads to elevation of invasiveness and migration of colorectal cancer cells in the future study." (PMID 34916487, 2021). "The expression of RAB27B, which was activated by β‐catenin/TCF‐4, was also required for the release of Exos from colorectal cancer stem cells." (PMID 33207034, 2021). "Several pieces of evidence have shown the tumor suppressor role of TCF4, in suppressing the adenoma–carcinoma transition, tumorigenesis, and progression in colorectal cancer." (PMID 33917757, 2021). "β-Catenin has been shown to bind directly to the ZEB1 promoter and activate its transcription in colorectal carcinomas, and the β-catenin/TCF4 complex induces the EMT activator ZEB1 to regulate tumor invasiveness." (PMID 33525359, 2021). "TRIB3 can interact with β-catenin and transcription factor 4 in intestine cells to increase expression of genes that are relevant with cancer stem cells in colorectal cancer." (PMID 32457797, 2020). "Specifically, SNC blocked β-catenin transcriptional activity by preventing β-catenin/TCF4 complex formation in colorectal cancer cells." (PMID 33347461, 2020). "In colorectal cancer cells, with the assistance of a neighboring cis-acting lincRNA, TCF4/β-catenin complex was recruited to the Ascl2 enhancer immediately downstream of the Ascl2 locus to drive high-level Ascl2 expression." (PMID 33109217, 2020). "We have shown that E2 promoter binding factor 1 (E2F1) suppresses Wnt/β-catenin activity through transactivation of β-catenin interacting protein 1 (CTNNBIP1), also known as inhibitor of β-catenin and TCF4 (ICAT) in human colorectal cancers." (PMID 32326181, 2020). "As for other LHX members, early studies revealed that LHX2 promoted tumor cell proliferation in pancreatic ductal adenocarcinoma, and LHX4 facilitated the development of colorectal cancer, both via enhancing Wnt/TCF4/β-catenin pathway." (PMID 31788020, 2019).
colorectal cancer (continued). "Resveratrol dose-dependently decreased exogenously overexpressed Myc-tagged TCF4 protein in colorectal cancer cells and increased TCF4 phosphorylation through ERK- and p38-MAPK-modulated pathways." (PMID 29495357, 2018). "Sequencing of primary colorectal tumors has identified a gene fusion in approximately 3% of colorectal cancer patients of the VTI1A and TCF7L2 genes, encoding a VTI1A-TCF4 fusion protein containing a truncated TCF4." (PMID 29975781, 2018). "Our present study clearly showed that the stress response gene ATF3 is a direct target for TCF4/β-catenin binding and plays a role in the suppression of cancer cell invasion and migration in human colorectal cancer cells." (PMID 29966001, 2018). "TCF4 is the major nuclear mediator of canonical Wnt signaling in the mouse intestine and human colorectal cancer cells." (PMID 30200414, 2018). "For example, in colorectal cancer, the interaction of CtBP2 with TCF-4 can activate its transcription activity, leading to activation of the downstream target gene β-catenin and resulting in cell migration." (PMID 30151388, 2018). "One report showed that there was a connection between CD133 and EGR1 and emphasized the importance of the EGR1/TCF4/CD133/LGR5 network in colorectal cancer." (PMID 29246166, 2017). "DDX3 also affects cell cycle progression by regulating Wnt/β-catenin-TCF4 signal to drive colorectal cancer." (PMID 28402257, 2017). "Polymorphic variants within TFAP2A have also been shown to interact directly with APC and β-catenin preventing β-catenin from associating with TCF4 and thus blocking transcription of WNT-responsive genes in colorectal cancer cells." (PMID 26697505, 2016). "HNF4α has also been found to compete with TCF4 and AP-1 at overlapping motifs to regulate distinct genes involved in proliferation and inflammation in colorectal cancer." (PMID 27228072, 2016). "TNIK phosphorylates S154 of TCF4, and its catalytic activity has proved to be essential for the colorectal cancer growth." (PMID 27650168, 2016). "Downstream signaling events are activated through the complex of β-catenin/TCF4, and aberrant regulation of β-catenin leads to progression of colorectal cancer." (PMID 25961950, 2015). "The findings from this study revealed an inherent role of 5-HT1DR which binds Axin1 and dissociates β-catenin from the complex, moving β-catenin into the nucleus to activate the β-catenin/LEF1/TCF4/MMP-7 pathway in colorectal cancer metastasis." (PMID 26214021, 2015). "In fact, compared to β-catenin knockdown, TCF4 knockdown shows better efficacy to induce growth arrest and apoptosis in human colorectal cancer cells." (PMID 25961950, 2015). "We performed Western blot and RT-PCR to compare the expression of TCF4 in different human colorectal cancer cells." (PMID 25961950, 2015). "We also tested the effect of resveratrol on TCF4 expression using other human colorectal cancer cells." (PMID 25961950, 2015). "The expression patterns of TCF4 and β-catenin were variable in different types of human colorectal cancer cells." (PMID 25961950, 2015). "KY-05009 inhibition of TGF-β1-induced activation of TCF4-mediated transcription in A549 cells is consistent with a previous study, which showed similar results in colorectal cancer cells." (PMID 25337707, 2014). "Beta-catenin, as a transcription factor complexed with TCF4, is known to upregulate expression of many relevant proteins in colorectal cancer, such as c-myc, cyclin D1, LEF-1, CD44, and c-jun." (PMID 22682314, 2012). "This study demonstrates different prognostic values of LEF-1 and TCF4 expression in colorectal cancer patients indicating different regulation of these transcription mediators during tumour progression." (PMID 21092222, 2010). "To investigate the localisation of LEF-1 and TCF4 in human colorectal cancer, we evaluated the expression of these proteins by immunostaining on tissue microarrays." (PMID 21092222, 2010).